E2F1 (E2F transcription factor 1)
Diseases named in the same sentence as E2F1 in open-access papers (continued):
Sharing a sentence is not in itself a finding about the gene and the disease.
tumor (continued). "Previous studies indicated that like E2F1, E2F2 exhibited oncogenic or tumor suppressive activity, and overexpression of E2F2 contributed to the development of several solid tumors, indicating worse patient outcome." (PMID 30967995, 2019). "One example is our observation that E2F pathway signatures were elevated in the MMTV-PyMT model, and we ultimately validated the role for E2F1, E2F3, and E2F3 in tumor progression using mouse models." (PMID 31341204, 2019). "Eight miRNA-449-family target genes (CDC25A, SIRT1, GMNN, E2F1, E2F3, BCL2, CDK2, and CCNE2) were selected; all of them involved in tumor development, cell cycle, and apoptosis." (PMID 30926829, 2019). "To date, several target mRNAs ascribed to miR-205 including PTEN and SHIP2, such as tumor suppressors, HER3, E2F1, E2F5, and PKCε, and oncogenes were identified." (PMID 31514456, 2019). "The genes, ZWINT, E2F1, HMGB2, KPNA2, and CKS2, were expressed at low or moderate levels in non-tumor tissues." (PMID 31695969, 2019). "As transcription factor E2F1 is known to regulate the cell cycle, proliferation, apoptosis, and differentiation and is involved in tumor invasion and metastasis, we sought to determine the effect of TGF-β1 on the expression of E2F1." (PMID 32010624, 2019). "In astrocytomas and glioblastomas, upregulation of E2F1 correlated with increased HELLS expression and increased along with tumor grades." (PMID 30220967, 2018). "E2F1 upregulated expression of lnc-GASL1 and led to decreased cell proliferation and in vivo tumor growth." (PMID 30518750, 2018). "Furthermore, it was determined that PARPi alters the activation status the endogenous inhibitor of E2F1 function, the retinoblastoma tumor suppressor (RB), wherein PARPi resulted in enrichment of hypophosphorylated (active) RB, suggesting that the functions of PARP‐1 suppression may be pleiotropic." (PMID 30467127, 2018). "mir-122 is a tumor suppressor that is directly inhibited by MYCC and that, in turn, represses MYCC via its repression of E2f1 and Tfdp2." (PMID 29880060, 2018). "The correlation between the NCK1-AS1 expression and these transcription factors E2F1, XBP1 and SP1 were performed and correlation analysis revealed that NCK1-AS1 has a significantly positive correlation with SP1 in TCGA CESC Tumor data set." (PMID 29416014, 2018). "For instance, it promotes tumor progression and metastasis through the miR-200a-3p/ZEB1 signaling pathway and promotes tumor angiogenesis in liver cancer through miR-107/E2F1/SPHK1 signaling." (PMID 29495592, 2018). "E2F1 and NFE2L2 overexpression values were both higher than expected by TCGA data, and even more elevated in metastasis than in primary tumours." (PMID 29743718, 2018). "Our model predictions revealed a common impact of E2F1 and TGFB1 signaling on tumor invasiveness in both cancer types." (PMID 28775339, 2017). "For patient #11, with E2F1 germline alteration at the MIR205-5p target site, gene expression in the tumor tissue was similar to that seen in normal tissue." (PMID 28704519, 2017). "HULC was further found to sequester miR-107, a known regulator of E2F1, resulting in a cascade of upregulated E2F1, increased SPHK1 activation, and eventually, tumor angiogenesis." (PMID 30159431, 2017). "Myc and E2F transcription factor 1 (E2F1) have profound roles in cancer; both can promote tumor growth and also induce apoptosis, highlighting the complexity of transcription factor activities in cancer." (PMID 29050362, 2017). "A more aggressive tumor phenotype is also found in double transgenic mice, c-MYC and E2F transcription factor 1 (E2F1)." (PMID 28422055, 2017). "From the remaining differentially expressed genes, 11 belonged to the apoptosis pathway, in which E2F1 and CLSPN were deregulated in 14 and 12 tumour types, respectively." (PMID 28387377, 2017).
tumor (continued). "miR-223 has been found to affect the cell cycle by regulating E2F1 35, migration and invasion in cancer cells by targeting EPB41L3 36, proliferation and tumor growth of cells by targeting IGF1R and downstream Akt/mTOR/p70S6K signaling pathway 37,38." (PMID 29090068, 2017). "The transcription factors E2F1, NF-κB, Sp1, HIF-1, AP-1, STAT3, and STAT5 play important roles in tumor cell signal transduction." (PMID 27613831, 2016). "The transcription factors, such as E2F1, NF-κB, Sp1, HIF-1, AP-1, STAT3, and STAT5, play important roles in tumor tube formation." (PMID 27613831, 2016). "It was reported that ablation of E2F1, E2F3 or E2F4 in Rb+/− mice significantly suppressed the development of pituitary tumors, extending the tumor-free lifespan of Rb1+/− mice." (PMID 26992224, 2016). "E2F1 (red) and ISX (green) were more strongly expressed and colocalized in tumor masses than those in adjacent healthy liver tissues in samples obtained from HCC patients." (PMID 27175585, 2016). "Yet, while E2F1 may be an important tumor suppressor, when this transcription factor interacts with cofactors commonly expressed by tumor cells with defective cell death signaling pathways, it participates in feedback loops that can contribute to tumor aggressiveness and chemoresistance." (PMID 27613060, 2016). "As such, E2F1/FOXO1 apoptotic and tumor suppressive functions are disabled during normal growth, and in emerging tumors, by the coordinated signaling of the PI3KCA and AKT, which directly disables FOXO1 function." (PMID 25907958, 2015). "This was investigated and validated through traditional genetic studies, and the role of E2F1 and E2F2 was shown in tumor metastasis." (PMID 26682278, 2015). "As an example miR-205 is known to be down-regulated in TNBC55, it is a known tumour-suppressor-miR that targets E2F1, LAMC1, suppresses cell proliferation, cell cycle and tumour growth." (PMID 26537449, 2015). "We found that levels of molecules cyclin D1, CDK4, E2F1 and PCNA were increased significantly in the tumor lysates of metformin administered mice as compared to control, while p21 level was diminished." (PMID 26484566, 2015). "The in vivo effect of E2F1 and ICAM-1 expression on DU145-derived tumor growth was evaluated in the xenograft mouse model." (PMID 24742333, 2014). "In this investigation, we observed that p15 and p16, two tumor suppressors that are upstream regulators of CDK4 were positively modulated by let-7c, whereas CDK4 and E2F1 were negatively regulated by let-7c in NPC cells." (PMID 24751144, 2014). "Previous studies reported that transcription factor E2F1 is expressed strongly in 59.8% of ESCC and that the overexpression is correlated with tumor progression, lymph nodemetastasis, and poor prognosis after surgery." (PMID 25373738, 2014). "To date, only E2F1 and MYCN have been shown to be direct activators of Bmi1 transcription in some kinds of cancers, and data regarding Bmi1 in tumor biology are far from complete." (PMID 24559156, 2014). "E2F1 and E2F4 are also identified as TFs with higher activities in tumor epithelium samples, suggesting higher proliferative rate of malignant epithelium breast cells." (PMID 23885756, 2013). "In the present study, the expression patterns of a number of tumor-related classical genes (eg, VEGF, PGF, FGF18, AKT, E2F1, ATF5) within our microarray dataset were detected as predicted." (PMID 22962576, 2012). "E2F1 is a key transcriptional regulator of DNA replication and cell-cycleprogression, and is negatively regulated by the RB1 tumor suppressor." (PMID 21629784, 2011). "These experiments led to the discovery that PXR is directly involved in suppression of tumour growth through functional regulation of cell-cycle progression through induction of p21WAF1/CIP1 and reduction of E2F1 expression." (PMID 20531417, 2010).
tumor (continued). "We investigated cell proliferation, cell cycle distribution, pRb phosphorylation, and mRNA expression of E2F-1 and PCNA in tumor cells after treatment with CKIA and CKIB." (PMID 19551155, 2009). "In fact, a large subset of patients classified with very favorable outcome shared a common molecular tumor phenotype characterized by ER-positive and/or ERBB2-negative status and low proliferation (low levels of E2F1 as well as BIRC5,TYMS,TOP2A and TK1)." (PMID 17535433, 2007). "Alternatively, we reported here that targeting the downstream core cancer drivers (CDRs) of RB1/E2F1, either through gene silencing using specific CRISPR-Cas13 or with small molecular inhibitors, may achieve anti-tumor goals." (PMID 41492471, 2026). "Our results show that the tumor suppressor genes were not activated by the physiological E2F1 activity induced by serum stimulation and activated by distinct E2F1 activity in epithelial cells." (PMID 41511373, 2026). "We further investigated contexts of these spMOCA’s hub genes, where we identified specific prognostic genes serves as hub genes in the same tumor type, for example, WIPF2 and CASC3 for BRCA, COX6A1 and PRAP1 for CRC, E2F1 and AKR1C3 for LUSC, and TSPAN3 and SLC4A11 for OVCA." (PMID 41370198, 2025). "Solar UV–induced DNA damage robustly induces CD70 expression via E2F1, which in turn mediates keratinocyte and cSCC cell proliferation through MAPK and NF-κB signaling, driving the expression of inflammatory mediators and tumor-promoting factors such as IL1B." (PMID 41510255, 2025). "Given the role of E2F1 as an upstream regulator of HMGCR, we reasoned that E2F1 might be responsible for ferroptosis resistance of immune refractory tumor cells." (PMID 41339438, 2025). "WPMY-1 cells, while sharing some TFs, showed higher activity of TFs associated with cell cycle regulation and proliferation, such as E2F family members (E2F1, E2F4, E2F8) and JUN, highlighting key regulatory differences between tumor-derived CAFs and benign stromal fibroblasts." (PMID 41198614, 2025). "Normally, miR-187-5p acts as a tumor suppressor by blocking cell cycle progression, and when miR-187-5p is absent due to HBx inhibition, E2F1 expression increases, facilitating the G1 to S phase transition and driving unchecked cell proliferation." (PMID 40625740, 2025). "Finally, it was also confirmed using clinical samples that E2F1 levels were markedly high in LUAD and positively correlated with clinical parameters such as tumor stage, invasion, and distant metastasis." (PMID 40886002, 2025). "E2F1 expression was significantly increased by the greatest multiple in the high stemness score group compared to SOX2 and MYC, as well as in the tumor and adjacent normal tissues group, early(I + II) and advanced stage (III + IV) group." (PMID 40886002, 2025). "High expression of E2F1 is correlated with the reduction of the tumor volume, independent of tumor location and lymph node metastasis." (PMID 40661777, 2025). "Additionally, the differential expression of E2F1 and MDM2 proteins in response to the intervention indicates a shift towards a more favourable tumour microenvironment." (PMID 40111872, 2025). "Moreover, multiple tumor types—such as PAAD and COAD, where COA4 is highly expressed—also exhibit a positive correlation between E2F1 and COA4." (PMID 40936169, 2025). "Thus, PDCD11 upregulates C‐MYC protein but not C‐MYC mRNA to activate downstream effector molecules including but not limited to E2F1, CCNE2, and SKP2, thereby exerting its tumor‐promoting functions." (PMID 40051297, 2025).
tumor (continued). "E2F1 contributed to the overexpression of SBF2-AS1, which led to the upregulated expression of GRB2 through sequestering miR-362-3p, ultimately facilitating tumor metastasis." (PMID 39119602, 2024). "Five transcription factors (CREB1, CTCF, YY1, E2F1, MYBL2) were significantly elevated with tumor progression in HCC, indicating that these potential transcription factors may be responsible for the upregulation of H3–H4 histone chaperones in HCC." (PMID 38561384, 2024). "Moreover, the dysregulation of cell-cycle-regulated genes (PLK1, CCNB1, CDKN2A, CCNE2, E2F1, and E2F2) by miR-5100 consistently resulted in upregulation in tumor tissues." (PMID 39590378, 2024). "In addition, reports have shown that GAS5 interacts with some proteins, such as E2F1, E2F4, YBX1, EZH2, and YAP, which inhibit tumor progression." (PMID 38782769, 2024). "A bioinformatics study performed by Dong and Zhan (2022) has annotated several distinct lncRNA/miRNA/E2F1 regulatory loops in the tumor formation of HCC, although lacking experimental evidence." (PMID 39119602, 2024). "The E2F1-mediated inhibitory pathway of WNT5A expression and the CXCL12/CXC- chemokine receptor 4 (CXCR4) chemokine receptor signaling pathway facilitate the invasion of circulating tumor cells into the brain." (PMID 39328239, 2024). "Interestingly expression was detected mainly in the cytoplasm (E2F1) and both cytoplasm and nucleus (E2F8) of tumor cells." (PMID 38686617, 2024). "Correlations between E2F expression and tumor stage in LUAD patients were also analyzed and we found that those of E2F7/8 were significantly associated with tumor stage (P < .05), while those of E2F1/2/3/4/5/6 were not (P > .05)." (PMID 38241554, 2024). "There was a 37% reduction in tumor weight along with a significant decrease in staining for Ki67, CCND1, and E2F1; a significant increase in nuclear staining for cleaved caspase 3; and reduced staining for TGF-β3 and Masson’s trichrome in the tranilast treated mice." (PMID 37445642, 2023). "Moreover, IHC staining images of mouse tumor tissue confirmed that GSG2 and E2F1 expression was reduced in the GSG2 knockout group compared with the control group." (PMID 37537694, 2023). "A protective DNA damage reaction increases apoptosis through E2F1-Foxo because it stabilizes E2F1 through ATM and Chk2 phosphorylation, whereas the Foxo-dependent arm of E2F1 signaling in charge of apoptosis was found to be reduced in most tumor types examined relative to counterpart normal samples." (PMID 37754262, 2023). "Surprisingly, the mRNA expression of only one gene, E2F1, showed a correlation with tumor stage that did not overlap with the afore-identified genes." (PMID 36768994, 2023). "Notably, we found substantial connections between the expression of BIRC5, E2F1, SFN, and UBE2C and the pathological stage of HCC, indicating their potential as indicators of tumor progression and severity." (PMID 38283837, 2023). "As a responsive gene of c-MYC and E2F1, CDCA7 participates in tumor transformation." (PMID 37510310, 2023). "Importantly, the functional studies showed that the tumour-suppression role of SETD7 is related to its methylation of oncogenic target proteins (Dnmt1, E2F-1 and HIF-1α) leading to their degradation." (PMID 35326563, 2022). "Generally, E2F1/E2F3, as an important node molecule of cell signaling network, participate in the transcriptional regulation of many important genes through dialogue with other signaling pathways, including NF-κB, and are tumor therapy targets." (PMID 36175803, 2022). "Cytoplasmic expression of E2F1 in lung tissue was higher in the non-metastatic 67NR and metastatic 4TLM groups compared to the tumor-free group and was strongly expressed in metastatic areas in the 4TLM group (p ˂ 0.05)." (PMID 36142156, 2022).
tumor (continued). "The expressions of E2F1 and MNX1-AS1 in the tumor tissues were also decreased by acRoots." (PMID 35152841, 2022). "E2F1 binds directly to the promoter region of DUSP1 and activates its transcriptional activity, thus dephosphorylating MAP kinases, inducing apoptosis and suppressing tumour growth." (PMID 35844791, 2022). "The negative correlation between activation of E2F1 (T2-1N) and stemness score is not surprising given the fact that tumor cells are believed to be in either a proliferative or a stemness state." (PMID 36213002, 2022). "It turned out that the elevated E2F1 level under hypoxia is actually essential for the expression of splicing factor SRSF7, which in turn contributes to the spliceomic adaptation in response to tumor hypoxia." (PMID 34362878, 2021). "We anticipate that cooperation with E2F1 to increase the transcription response stands for an important but not the only mechanism interpreting the tumor-promoting capacities of Pontin." (PMID 33542204, 2021). "By using a xenograft mouse model, we showed that ectopic expression of USP2-AS1 promoted in vivo xenograft tumor growth of control cells, but not E2F1 knockdown cells." (PMID 34707111, 2021). "The expression of miR‐107, E2F1, and CCND1 in the tumor tissues was examined." (PMID 34758200, 2021). "Like E2F1, CCNE2 was also involved in tumor invasion, proliferation, and migration." (PMID 34521301, 2021). "Accompanying the accelerated tumor growth by c-Myc overexpression, expression levels of both USP2-AS1 and E2F1 were elevated in xenografts generated from c-Myc-overexpresed HCT116 cells, indicating that c-Myc may promote tumor growth via USP2-AS1." (PMID 34707111, 2021). "p16ink4a exerts tumor suppressive function by inhibiting the activities of the cyclin D-dependent kinases, CDK4 and CDK6, and preventing the retinoblastoma protein (Rb) phosphorylation and dissociation from the transcription factor E2F1." (PMID 34277422, 2021). "The E2F1-induced activation of the SLC16A1/SLC16A1-AS1 could lead to changes in downstream genes that mediate their effects on metabolism and tumor aggressiveness." (PMID 32863950, 2020). "Other candidate markers with significantly altered mRNA levels from the qPCR array (SP1, E2F1, TCF7L2) exhibited comparable levels between tumor and adjacent normal tissues using immunohistochemistry without evident heterogeneity in terms of spatial distribution (data not shown)." (PMID 33063251, 2020). "First, we tested the expression of E2F1, a known target gene of miRNA based on our previous data in tumor mice treated with miR-302b mimics and negative control with or without cisplatin." (PMID 32806777, 2020). "However, similarly to E2F1, we found a positive relationship between MYC expression and tumour invasiveness, although only in the ST subtype." (PMID 32316225, 2020). "Suppressing PI3Kδ reduces E2F1 expression also in non-EBV infected tumour cells, demonstrating that this pathway is also active in rapidly proliferating cells." (PMID 32453417, 2020). "The mRNA translation stress pathway is not unique for EBV-carrying cells and depletion of PI3Kδ suppresses E2F1 expression also in non-EBV-carrying tumour cells." (PMID 32453417, 2020).